EPHA2 (EPH receptor A2)
Diseases named in the same sentence as EPHA2 in open-access papers (continued):
Sharing a sentence is not in itself a finding about the gene and the disease.
tumor (continued). "The design of EphA2-ILs-DTXp enables efficient and specific delivery of a large payload of docetaxel to tumor cells, while reducing toxicity compared to conventional chemotherapy." (PMID 33092175, 2020). "The context‐dependent EphA2 signaling can occur via ligand‐induced tyrosine auto‐phosphorylation, generally considered tumor‐suppressive, or via oncogenic, ligand‐independent phosphorylation of the S897 residue." (PMID 32115889, 2020). "Then, we searched the GEPIA database and found bioinformatics information indicating that EphA2 expression was significantly higher in GBM tumor tissues than in normal tissues." (PMID 32116702, 2020). "EphA2 is upregulated at the gene and protein levels in human tumor tissue specimens and established cancer cell lines." (PMID 32811512, 2020). "The tyrosine kinase EphA2, which belongs to the family of Eph receptors, is highly produced in tumor tissues, while found at relatively low levels in most normal adult tissues, indicating its potential application in cancer treatment." (PMID 32811512, 2020). "We found that EphA2 knockdown significantly reduced tumor size, tumor weight, and tumor volume in the 786-O-R subcutaneous tumor model." (PMID 32814829, 2020). "As specified above, the Akt activation of EphA2 increases tumor cell motility by promoting migration and invasion." (PMID 32203105, 2020). "In the carboplatin‐treated tumors, EphA2‐pS897 and clCasp3 localized to different tumor cells and areas." (PMID 32115889, 2020). "The combination of EphA2-ILs-DTXp and gemcitabine led to complete tumor regressions in almost all animals in both BL-0293 and BL-0382, which were superior to either drug alone." (PMID 33092175, 2020). "After treatment, EphA2 (total and pS897) was enhanced and the tumor‐suppressive EphA2‐pY588 decreased in OVCAR4." (PMID 32115889, 2020). "We next performed IHC on sequential GS tumour tissue sections to determine the localisation of αDG, βDG, EphA2 and EphA3." (PMID 31463571, 2019). "The tumor-promoting effects of EPHA2 are mediated by ligand-independent signaling involving serine S897 phosphorylation." (PMID 31160603, 2019). "Experiments with ephrin‐A1‐Fc fusion protein, a soluble chimeric protein that activates EPHA2, showed that EPHA2 has tumor‐suppressing activity." (PMID 30548122, 2019). "The oncogenic function of EPHA2 is ligand-independent, as exogenous ephrin-A1 stimulation inhibits tumor cell proliferation." (PMID 31160603, 2019). "EphA2 siRNA incorporated in DOPC nanoliposomes was greatly effective in lowering EphA2 protein levels after a single dose, and significantly reduced tumor growth three weeks after treatment." (PMID 31064156, 2019). "Overall, our results suggest that EphA2 signaling promotes tumor metastasis by inducing VM formation during gastric tumorigenesis." (PMID 30833656, 2019). "In agreement, we reported that SLAP attenuates tumour cell dissemination via destabilisation of the adhesive receptor EPHA2." (PMID 31091767, 2019). "Statistically, high expression of EphA2 was found to be significantly correlated with tumor size (P = 0.0416), lymph node metastasis (P = 0.018), lymphovascular invasion (P = 0.013), and TNM stage (P = 0.035)." (PMID 30833656, 2019). "In the assay performed under these conditions, the cytotoxic activity of T cells in freshly isolated cells from lung tumor tissues was analyzed under a co-culture with a tumor cell line (U251) expressing EphA2 and EphA2-specific BiTE." (PMID 30796310, 2019). "To study the MTD of EphA2 siRNA –encapsulated liposomes, evaluate efficacy in the tumor cell, which we cannot be cured by treatment." (PMID 31708785, 2019). "In our analysis, each treated well consisted of U251 cells and freshly isolated cells from tumor tissues with EphA2/CD3 BiTE." (PMID 30796310, 2019).
tumor (continued). "Overexpressed EPHA2 promotes tumor cell proliferation, migration, invasion, and metastasis; and EPHA2 is activated through phosphorylation at serine-897 by AKT, p90 ribosomal S6 kinases, and protein kinase A, but not by EPHRIN-A1." (PMID 31412935, 2019). "It has been reported that overexpression of EphA2 relate to tumor progression, metastasis, and prognosis in HCC." (PMID 29449527, 2018). "Compared with vehicle treatment, administration of ALW to tumor-bearing animals for 17 days significantly inhibited tumor growth in vivo, but the decrease was less prominent in the sh-EphA2 group than in the sh-NC group." (PMID 30451837, 2018). "Most reports have demonstrated that EphA2 mediates ligand-dependent inhibition and ligand-independent promotion of tumor migration and invasion." (PMID 30451837, 2018). "Immunocytochemistry analysis of tumor xenograft demonstrated less expression of MMP-9 in the mouse treated with EphA2-siRNA, suggesting that silencing of EphA2 gene down regulated the MMP-9 gene expression and exerted tumor inhibitory effects." (PMID 29861465, 2018). "Particularly, EphA2 supports tumor-propagating cells with stem-like characteristics to remain in an undifferentiated state in human GBM." (PMID 29682554, 2018). "Further analyses showed that EphA2 is basally phosphorylated (on Tyrosine) in about 30% of tumor areas with a strong immunostaining (f with a SI=6)." (PMID 29849945, 2018). "The EphA2-Src-siRNA DOPC had a less reduction rate of tumor growth than EphA2-FAK-siRNA DOPC-treated group." (PMID 29861465, 2018). "After couple years later, dual therapy of anti-FAK-siRNA along with anti-EphA2 in DOPC exerted significant tumor reduction (90%)." (PMID 29861465, 2018). "Recently, it was also found that EphA2 receptors are significantly involved in modulating tumour angiogenesis and that EphA2 is involved in blood vessel formation and remodeling during the vascular development of cancers." (PMID 30914876, 2018). "The results revealed that tumor tissues in group 2 mice (luc-LM3-shTR4 cells derived) had higher expression of EphA2 than tumor tissues in group 1 mice." (PMID 29449527, 2018). "Ephrin type A receptor 2 (EphA2), IL-13Ra2, and HER2 represent promising tumor associated antigens that have been targeted both pre-clinically and clinically using CAR T-cell therapy in the setting of GBM." (PMID 30740109, 2018). "In HeyA8 cell line, the size of the tumor for EphA2 targeted siRNA group was 0.98 g relative to control siRNA 1.51 g." (PMID 29861465, 2018). "EphA2 is a representative member of a 16-member superfamily of receptor tyrosine kinases and functions as a key mediator of tumor progression." (PMID 29449527, 2018). "In general, EphA2 works via Ephrin A1’s signaling axis to regulate multiple events in the transformation of tumour malignancies." (PMID 30914876, 2018). "For instance, ligand-dependent signaling induced by EphrinA1, a ligand of the EPH receptor A2 (EphA2), is tumor suppressive." (PMID 30451837, 2018). "EphA2-FAK-siRNA-DOPC exerted significant tumor growth reduction (90%) in comparison to EphA2-siRNA-DOPC (67%) and FAK-siRNA-DOPC (62%) in HeyA8 model." (PMID 29861465, 2018). "On the other hand, in the SkOV3ip1 cell line, the tumor volume for EphA2-targeted siRNA and control siRNA were 0.35 gm and 0.70 gm, respectively." (PMID 29861465, 2018). "In brain tumours, high expression of EphA2 is mostly detected in advanced grades of tumours, such as anaplastic astrocytoma and GBM." (PMID 30914876, 2018). "Small molecule inhibitors (FDA approved-Dasatinib) of EphA2 have significantly reduced tumor growth in several cancer types, and have shown anti-tumor efficacy via the reduction of EphA2 expression and kinase activity upon treatment." (PMID 30031396, 2018). "Some effects of EphA2 on tumor phenotypes are mediated by its physical and functional interaction with ErbB2/EGFR and activation of signaling pathways that involve Ras/MAPK and RhoA." (PMID 29682554, 2018).
tumor (continued). "Liposomal anti-EphA2-siRNA reduced 35–50% of tumor size, but when it was co-delivered with paclitaxel, tumor size reduction went up to 82% relative to the control group." (PMID 29861465, 2018). "While in SkOVi31 model, there was also notable reduction of tumor growth in EphA2-FAK-siRNA-DOPC (76%)-treated group compared to the EphA2- (50%) and FAK- (61%) treated group." (PMID 29861465, 2018). "EphA2 activation can suppress tumor cell growth and hence EphA2 has been established as a therapeutic target for malignant tumors by hindering the progression of tumor invasion." (PMID 30176889, 2018). "Our IHC evaluation of 168 sets of N/T tissue showed a statistical significant upregulation in tumor tissue compared with normal tissue for both EphA2 and EphB4 in the majority of the patients." (PMID 28165374, 2017). "Conversely, tumor cells in which EphA2 expression is down-regulated by small interfering RNA show reduced tumorigenic activity, such as slower cell proliferation, tumor sphere growth, and cell migration." (PMID 28686661, 2017). "Cells from control tumours were highly invasive, and this was significantly reduced by knockout of EPHA2 or RCP, consistent with a tumour cell-autonomous role for these proteins in invasive behaviour." (PMID 28294115, 2017). "More specifically, tumor-specific T cell response to tumor-associated antigens MAGE-6 and EphA2 is characterized by a predominance of T cells synthesizing IL5 and IL4, together with reduced levels or a complete absence of T lymphocytes expressing IFNγ." (PMID 28409322, 2017). "More recently, EphA2 has been shown to support drug resistance in a number of cancer models, further highlighting its multifaceted and direct role in tumor progression." (PMID 29290990, 2017). "MT1-MMP cleaves the N-terminal ligand-binding domain of EphA2 and inactivates its ligand-dependent tumor-suppressing activity." (PMID 29072678, 2017). "Growing evidence indicate that EphA2 plays an important role in cellular transformation, primary tumor initiation, progression, and angiogenesis, and tumor invasion." (PMID 29273006, 2017). "Although the phosphorylation of EphA2 at Ser897 has been previously reported to function in the ligand-independent promotion of tumor malignant progression, its role in infectious diseases need further investigation." (PMID 28957431, 2017). "In a preliminary evaluation on five sets of tumor and normal tissue sections, two different antibodies recognizing EphA2 and two different antibodies recognizing EphB4 showed similar staining patterns." (PMID 28165374, 2017). "miR-302b exhibited anti-tumor activity by reversing EphA2 regulation, which relayed a signaling transduction cascade that attenuated the functions of N-cadherin, β-catenin, and Snail (markers of Wnt/β-catenin and epithelial-mesenchymal transition, EMT)." (PMID 29273006, 2017). "EphrinA1 is the most extensively studied ligand for EphA2 in cancer, although EphA2 can be activated by other EphrinA ligands in cancer cells and tumor vasculature." (PMID 28752098, 2017). "We identified 60 miRNAs, among which six miRNAs (miR-200a/miR-200b, miR-26a/ miR-26b, miR-141, miR-520d-3p) had been reported to target EphA2 in a few tumor types." (PMID 29273006, 2017). "While many of the invasive and metastatic properties of EphA2 are attributed to ligand-independent signaling ephrin A1-mediated ligand activation of EphA2 is generally antagonistic in action, leading to cell repulsion and tumor suppression." (PMID 29290990, 2017). "We demonstrated that miR-302b serves as a critical tumor suppressor of GC cell proliferation, invasion, and migration by modulating the EphA2/Wnt/ β-catenin/EMT signaling cascade." (PMID 29273006, 2017). "The results show a significantly enhanced staining intensity and more widespread distribution in tumor tissue compared with adjacent normal tissue for EphA2 as well as EphB4." (PMID 28165374, 2017).
tumor (continued). "The signaling effects of EphA2 and EphB4 in cancer are complex, and not only tumor-promoting but also tumor-suppressing effects have been reported for these receptors." (PMID 28165374, 2017). "As a member of RTK family, it is well known that EphA2 is an emerging target for cancer therapeutics, due to its increased expression in tumor tissues." (PMID 29273006, 2017). "We decided to evaluate one of the next candidates on the list, EphA2, a member of the Eph family of receptor tyrosine kinases that is preferentially expressed in tumor tissue compared to normal tissue and plays an important role in cancer malignancy." (PMID 28165374, 2017). "Staining for EphA2 and EphB4 was generally present in epithelial cells throughout the whole tumor area consisting of 2 or 3 TMA cores." (PMID 28165374, 2017). "As seen in in vitro co-culture studies, EphA2, EphB2 and EphB4 phosphorylation was reduced in whole tumour lysates of Tie2PEKO animals, independently of changes in gene expression." (PMID 28719590, 2017). "Although Hsp90 has a well-established intracellular role in mediating the folding and activity of numerous clients, including EphA2, cell surface and secreted forms of eHsp90 are frequently reported in tumor models." (PMID 29290990, 2017). "By contrast, cells from RCP and EPHA2 knockout tumours formed closely-knit colonies with a defined edge and little indication that cells were able to migrate away from the colonies)." (PMID 28294115, 2017). "EphA2 was previously found in infiltrative and tumor-initiating cells and EphA3 is also overexpressed in the invading ring of the tumor." (PMID 27494882, 2016). "Consistently, SLAP inactivation in CRC dramatically increases EPHA2 protein level and amplifies the SRC/EPHA2/AKT signaling cascade that promotes tissue invasion of tumor cells." (PMID 26788993, 2016). "Since CT26 cells express undetectable levels of ephrin ligands, CT26 cells are a good experimental model for EphA2-mediated tumour growth." (PMID 27619642, 2016). "The novel eA5-based cytotoxin was neutral to normal cells tested, but effectively killed tumor cells demonstrating overexpression of EphA3, EphA2, and EphB2 receptors." (PMID 27494882, 2016). "Together, our findings demonstrate Anks1a-regulated EphA2 ER export significantly enhances the level of EphA2 at the cell surface and consequently enhances tumour growth." (PMID 27619642, 2016). "The short TAT peptide labeled with FITC was used to facilitate intranuclear delivery, while the YSA peptide tagged with the BHQ1 quencher group was used to specifically bind to the tumor EphA2 membrane receptor." (PMID 27661121, 2016). "Its tumor suppressor function is mediated by dominant-negative inhibition of EPHA2 dimerization and activation, thus blocking oncogenic EPHA2 signaling." (PMID 27533460, 2016). "To investigate EphA2-mediated tumour growth, we used CT26 cell lines expressing one of two shRNAs (shRNA-17 or -21) specific to Anks1a (first panel)." (PMID 27619642, 2016). "We produced a highly potent eA5-based cytotoxin that kills tumor cells over-expressing receptors EphA3, EphA2, and also EphB2." (PMID 27494882, 2016). "TF and EphA2 have separately been reported to be expressed in various cancers, but our study is the first to demonstrate co-expression in the same tumor specimens." (PMID 27246245, 2016). "The EphA2-ECD-Fc also had anti-tumour and anti-angiogenic effects on human xenografts, and in orthotopic models of pancreatic cancer." (PMID 26620208, 2016). "EphA2 Ser897 was previously shown to drive migration propensity of tumor cells and our study reveals that EphA2 stays phosphorylated on Ser897 in the Ephrin B3/EphA2 complex in NSCLC cells of different histology." (PMID 27533087, 2016).
tumor (continued). "While media of CD19-ENG T cells contained 129.4 ± 79.0 ng/ml CD19-ENG molecules (range 39.7–223 ng/mL; 95%CI 46.6–212.3), no CD19-ENG molecules were detected in media from T cells secreting an ENG specific for an irrelevant tumor antigen (EphA2-ENG T cells)." (PMID 27255991, 2016). "Genetic and pharmacological inhibition of EPHA2 induces apoptosis and abrogates tumorigenic growth of tumor cells." (PMID 27681698, 2016). "Ephrin-A1 ligation of EphA2 and subsequent receptor activation has been proposed to be tumor suppressive, although other studies point to an important role for kinase dependent EphA2 activity in cancer development." (PMID 27246245, 2016). "Previous studies have reported an elevated expression level of EphA1 and its analogue, EphA2, in the tumor tissue of HCC patients." (PMID 27066828, 2016). "EphA2 is known to form a complex with ErbB2/HER2/Neu that is important for tumour initiation and metastasis in MMTV-Neu transgenic mice." (PMID 27619642, 2016). "Along this line, it was shown that co-expressed in the same tumor cell Ephrin A3 binding in cis (ligand and receptor on the same cell) can block EphA2 and EphA3 in trans (ligand and receptor on different cells) ligand binding." (PMID 27533087, 2016). "We demonstrated that drug conjugates via such agents induce receptor activation and internalization of the drug selectively to EphA2 expressing cancer cells and tumor vasculature [28−31]." (PMID 26959746, 2016). "Given our in vitro results, we analyzed as to what extent Ephrin B3, Ephrin A1 and EphA2 were expressed in early stage IA-IB NSCLC tumor specimens." (PMID 27533087, 2016). "While ligand-dependent EphA2-activation has been considered tumor suppressive, recent reports have highlighted a role for EphA2-ephrin-A1 signaling in tumor cell plasticity and a shift from mesenchymal to amoeboid morphology and increased single cell invasion." (PMID 27246245, 2016). "These anti-tumour effects were proposed to occur, to some extent, by EphA2-mediated cell detachment, inhibition of tumour cell migration, and indirect activation of apoptosis." (PMID 27537875, 2016). "EphA3 was detected in the perivascular space, but it showed a limited co-staining with EphA2 within the tumor area." (PMID 27494882, 2016). "We also investigated if combined expression of TF and EphA2 was related to tumor characteristics in primary tumors." (PMID 27246245, 2016). "EphA2 was found on endothelial cells of tumor neovasculature, as reported, and in the surrounding areas." (PMID 27494882, 2016). "Tumor cells that overexpress EphA2 exhibit enhanced malignant cellular behavior such as resistance to apoptosis and cellular invasiveness." (PMID 26177500, 2015). "As a member of the family of receptor tyrosine kinases (RTK), EphA2 plays a critical role in embryonic patterning, neuronal targeting, vascular development, and tumor progression, especially in EMT, which it is an attractive target for cancer therapy." (PMID 26510908, 2015). "Cumulatively, our results demonstrate that these two C3f-derived peptides are reflective of MMP-9 expression in tumor cells and can potentially be used as measures of EphA2 treatment efficacy." (PMID 25788424, 2015). "EphA2, a member of the Eph family, is overexpressed in tumor cells of various types of cancer including breast, prostate and colon." (PMID 26177500, 2015). "Noteworthy, the 17-DMAG-dependent inhibition of Hsp90 affects EphA2 stability, improving the in vivo anti-tumor activity of Hsp90." (PMID 26501335, 2015). "EphA2 staining of tissues from vehicle-only treated mice revealed extensive regions of tumor mass in the tumor-bearing side of the brain while the contralateral side did not display any EphA2-positive cells." (PMID 24346635, 2014). "Univariate and multivariate analyses indicate that the high expression level of EphA2 in tumor tissues is a prognostic factor in patients with RCC." (PMID 25013485, 2014).